LGALS3 (galectin 3)
Diseases named in the same sentence as LGALS3 in open-access papers (continued):
Sharing a sentence is not in itself a finding about the gene and the disease.
viral infection (continued). "Galectin-3 is a protein that plays a crucial role in various aspects of viral infections, making it an attractive target for antiviral therapy." (PMID 37298569, 2023). "Among the 12 human galectins, galectin-3 (Gal-3) is abundantly expressed during viral infections in a variety of immune cells (neutrophils, macrophages, monocytes, and dendritic cells), as well as in fibroblasts and epithelial and endothelial cells." (PMID 37112643, 2023). "Contrary to the enhancement of viral infection, galectin-3 has been shown to inhibit or interfere with viral infection." (PMID 36823664, 2023). "Galectin-3 plays a critical role in mediating tissue damage and inflammation during viral infections through its involvement in immune cell activation, cytokine production, and immune signaling pathways." (PMID 37298569, 2023). "Galectin-3 and Galectin-3-binding protein (Gal-3BP) both play significant roles in viral infections." (PMID 37298569, 2023). "Based on the best-fit linear trend line, we found a positive correlation (r = 0.9539, p = 0.0002) between levels of galectin-3 and viral NP proteins in the lung tissue during the acute phase of viral infection (right)." (PMID 36823664, 2023). "Immunoblot analysis of the lung tissue revealed a concomitant increase in the expression of galectin-3 and viral NP proteins, one of the major viral structural proteins expressed early after viral infection." (PMID 36823664, 2023). "Galectin-3 was recognized as a target to regulate viral immune response to modulate virus infection." (PMID 35437453, 2022). "Further unbiased investigation into the most expressed genes per cluster revealed a plethora of genes previously reported in the context of viral infections, such as Il7r, Tcf7, Zeb2, Klrg1, Gzma, Gzmb, Gzmk, Vim, Lgals3, Tox, Lag3, Pdc1, Id3." (PMID 35185882, 2022). "Galectin-3 expression is known to be induced in viral infections and by a multitude of molecules that either mimic or are characteristic of ongoing inflammation and microbial infection, such as IFN-α, IFN-β, IFN-γ, TNF-α, poly(I:C), dsRNA, and dsDNA." (PMID 36131342, 2022). "Galectin-3 participates in the mechanism of viral infections, such as human immunodeficiency virus (HIV) and influenza virus infections in viral binding, replication, budding, and transmission." (PMID 35845133, 2022). "Recent reviews even suggested the immune-regulatory functions of galectins (mainly Gal-1, galectin-3, and galectin-9) as potential therapeutic strategies for viral infection, especially for influenza A virus." (PMID 34559847, 2021). "Galectin-3 has been previously studied in relation to several viral infections in human, including human immunodeficiency virus, herpesvirus-1 infection, influenza, early herpes zoster neuralgia, and postherpetic neuralgia." (PMID 34439802, 2021). "Expression of these genes is associated with movement (MMP9, SPP1, ALCAM, and others), viral infection (APOC1, LGALS3, CD63, and others), and recruitment of phagocytes (APOE, CHI3L1, LGALS3, and others)." (PMID 32723919, 2020). "Galectin-3 was upregulated in antigen-specific CD8+ T cells responding to invading viral infections." (PMID 30388704, 2018). "We find that galectin-3 expression was upregulated at the transcriptional and at a protein product level upon viral infections as well in co-receptor-stimulated CD8+ T cells within 16 hr, and the expression further increased on 3 days post stimulation." (PMID 30388704, 2018). "This barrier effect has also been reported in corneal epithelial cells, whereby CA125 interacts with galectin-3 to serve as a barrier against bacterial and viral infection." (PMID 28881712, 2017). "Galectin-3, a chimeric type β-galactoside-binding protein, is known to modulate viral infection; however, its role in enterovirus 71 (EV71) infection has not been investigated." (PMID 28002441, 2016). "Nevertheless, the role of galectin-3 in viral infection deserves more emphasis and warrants further investigation." (PMID 28002441, 2016).
viral infection (continued). "In addition, a β-galactoside-binding lectin, galectin-3 (Gal3), has emerged as a pivotal player in host–pathogen interactions and viral infections." (PMID 39125989, 2024). "Galectin-3, a well-established participant in an array of cellular activities, has lately been identified as a significant orchestrator of various transcriptional pathways during viral infections." (PMID 37298569, 2023). "Galectin-3 modulates the immune response during viral infections." (PMID 37298569, 2023). "Extracellular galectin-3 may also promote nuclear import and/or export of the vRNP, resulting in enhancing viral infection." (PMID 36823664, 2023). "Moreover, galectin-3 exhibits pleiotropic biological functions and plays a dual role in virus infection." (PMID 36823664, 2023). "There are numerous reports linking galectin-3 with the course of various viral infections." (PMID 34439802, 2021). "Our results indicate that galectin-3 expression may be a useful biomarker of cardiac fibrotic degeneration in acute myocarditis following viral infection." (PMID 30673749, 2019). "Galectin-3 is crucial in innate immunity for bacterial and viral infection." (PMID 27240351, 2016). "Furthermore, our results also suggest that galectin-3 may enhance nuclear import and/or export of the vRNP complex, thereby promoting viral infection." (PMID 36823664, 2023). "Galectin-3 is a ß-galactoside binding lectin that can drive neutrophil chemotaxis, bind TLR4, and increase production of pro-inflammatory cytokines during viral infections." (PMID 37064248, 2023). "Galectin-3 has been found to enhance HIV-1 entry and infection up to 20-fold, suggesting a critical role in the early stages of viral infection." (PMID 37298569, 2023). "Indeed, many interferon‐related genes upregulated during viral infection in rats were found to be downregulated by PTS in this study (e.g., Oas1a, Oas2, Irf7, Ifi27, Lgals3 bp)." (PMID 39562169, 2024). "Galectin-3 could regulate immune responses in infectious diseases such as fungal nephropathy, streptococcus pneumonia, and HSC virus infection by controlling immune cell activation, recruitment, and differentiation." (PMID 35437453, 2022). "The pathophysiological role of galectin-3 in acute myocarditis following viral infection is not fully understood." (PMID 30673749, 2019). "Galectin-3 is also an agonist of Toll-like receptor 4 (TLR4) and can regulate the NOD-like receptor family pyrin domain containing 3 (NLRP3) inflammasome, promoting inflammasome assembly and activation, which contributes to enhanced inflammation and tissue damage in viral infections." (PMID 37298569, 2023). "The results of this study also suggested that Nramp and PAI regulated by LncRNA could facilitate virus infection and proliferation for infected cells respectively, while T cell leukemia homeobox 3 (TLX3), as well as galectin 3 function by lncRNA, may play a role in the resistance mechanism." (PMID 34290708, 2021).
renal failure (44 papers, 2011 to 2025). "Galectin-3 has been proposed as a candidate marker for cardiovascular risk stratification, although its role in kidney failure is unclear." (PMID 38519721, 2024). "That correlation, revealed in a group of patients with chronic systolic heart failure, demonstrated that high plasma galectin-3 concentration was associated with renal failure and shorter survival of the patients." (PMID 35053194, 2021). "In relation to the postoperative condition of patients with congenital heart diseases after cardiosurgical treatment, galectin-3 was studied in order to predict the risk of acute kidney injury during post-operative care, and the results of the larger cohorts are promising." (PMID 35410028, 2022). "Many studies have already concluded that galectin-3 strongly affects this organ’s fibrosis, and it has even been suggested that its measurement will allow to predict renal failure and patients’ survival." (PMID 35742776, 2022). "Galectin-3 (Gal-3) is a pleiotropic glycan-binding protein shown to be involved in sepsis and acute kidney injury (AKI)." (PMID 33736691, 2021). "It is worth to stress here, that in the case of heart or kidney failure it is recommended to analyse in serum galectin-3 concentration together with natriuretic peptide concentration values." (PMID 35053194, 2021). "The purpose of this study was to evaluate the relationship between preoperative levels of circulating Galectin-3 (Gal-3) and acute kidney injury after cardiac surgery." (PMID 30342486, 2018). "Here, we demonstrate that galectin-3 (Gal-3), a β-galactoside binding lectin that plays an important role in kidney fibrosis and renal failure, is one of the key factors for renal injury progression." (PMID 30455396, 2018). "Galectin-3 (Gal-3), a β-galactoside-binding lectin, is increased in kidney injury and its pharmacological blockade reduces renal damage in acute kidney injury, hyperaldosteronism or hypertensive nephropathy." (PMID 27829066, 2016). "Although galectin-3 is known to be upregulated in acute kidney injury, the relative importance of its different domains and functions are poorly understood in the underlying pathogenesis." (PMID 21494626, 2011). "In our study, we investigated roles of galectin-3 in the FA model of acute kidney injury using the natural inhibitor MCP." (PMID 21494626, 2011). "Additionalresearch is needed to confirm whether serum galectin-3 concentration couldpredict cardiovascular morbidity in individuals with renal failure." (PMID 39076571, 2024). "In patients with chronic and acute heart failure a relationship was observed between higher serum galectin-3 concentrations and renal failure parameters assessed by cystatin C or uric acid concentrations or by reduced estimated glomerular filtration rate (eGFR)." (PMID 35053194, 2021). "Interestingly, modified citrus pectin (a dietary supplement) has been used as an inhibiter of galectin-3 to block cardiac injury that is induced by acute kidney injury via the galectin-3 pathway and may provide an easy initial molecule for clinical trials." (PMID 33513858, 2021). "Targeting the KLF4/Galectin-3 axis with Kenpaullone and GB1107 confirmed protective effects against cisplatin-induced cell death and acute kidney injury, respectively." (PMID 41079936, 2025). "Therefore we experimentally modulated galectin-3 in folic acid (FA)-induced acute kidney injury utilising modified citrus pectin (MCP), a derivative of pectin which can bind to the galectin-3 carbohydrate recognition domain thereby predominantly antagonising functions linked to this role." (PMID 21494626, 2011).
glioblastoma (43 papers, 2011 to 2025). The most malignant astrocytic tumor (WHO grade IV). "Recently, a study indicated that LGALS3 can promote the therapeutic resistance of glioblastoma and is related to tumor risk and prognosis." (PMID 32528967, 2020). "In glioblastoma cells, galectin-3 expression was associated with its translocation to mitochondria, suggesting its involvement in mitochondrial homeostasis." (PMID 24764473, 2013). "Inhibition of galectin-3 expression led to increased cell death, indicating that galectin-3 acts as a prosurvival factor in very specific tumor microenvironments associated with glioblastoma progression." (PMID 24764473, 2013). "Galectin-3 expression was associated to a very specific tumor microenvironment, the pseudopalisades- areas of viable tumor cells surrounding necrotic areas that are commonly found in advanced stages of glioblastomas." (PMID 24764473, 2013). "Besides GL-Lect, galectin-3 was implicated in macropinocytosis in glioblastoma stem cells." (PMID 38750548, 2024). "Within this family, LGALS1, LGALS3, and LGALS9 have been most consistently implicated in glioblastoma progression, through roles in tumour proliferation, immune evasion, and resistance to therapy." (PMID 41516291, 2025). "Previous experimental work has also shown that LGALS3 supports the maintenance of glioblastoma cancer stem cell (CSC) populations, further contributing to chemo- and radioresistance and tumour re-population." (PMID 41516291, 2025). "Our data further reveals that ICI-resistant human glioblastomas are enriched in genes that induce IL-6, such as LGALS3, and downstream targets of the IL-6 signaling cascade such as p-STAT3, p-AKT, p-ERK1/2, and ANXA113,28,29." (PMID 40161763, 2025). "Our observation of elevated LGALS3 expression in glioblastoma is therefore concordant with these mechanistic findings and reinforces its biological relevance as a potential therapeutic target." (PMID 41516291, 2025). "In tumors, LGALS3 is upregulated in glioblastoma and can increase its sensitivity to radiotherapy and chemotherapy." (PMID 39794359, 2025). "Among those previously connected to glioblastoma development, LGALS3 is the most extensively characterized." (PMID 32488114, 2020). "Galectin 3 and integrin β1 overexpression in glioblastoma cells migrating along the white matter is typical of mesenchymal single cell migration." (PMID 31601895, 2019). "Another study reported that Galectin-3 as an immunohistochemical tool to distinguish pilocytic astrocytomas from diffuse astrocytomas, and glioblastomas from anaplastic oligodendrogliomas." (PMID 29312645, 2017). "An increase in galectin-3 expression has been reported in lymphomas, head and neck and thyroid carcinomas, glioblastomas and osteosarcomas." (PMID 22216245, 2011). "We and others showed that galectin-3 was found overexpressed in glioblastomas, especially within pseudopalisades, which are formed by migrating cells surrounding necrotic areas." (PMID 22216245, 2011). "Notably, genes such as CD276 (B7-H3), GATA3, and LGALS3 (galectin-3) have been shown to play significant roles in glioblastoma prognosis." (PMID 39068393, 2024). "Similarly, HIF2α contributes to glioblastoma progression by regulating genes such as GPx1, vasorin, beclin-1, and galectin-3, thereby influencing the response to oxidative stress, angiogenesis, autophagy, and cell survival." (PMID 38893207, 2024). "In the current study, we tried to study the expression of LGALS3 and LGALS3BP, their potential as prognostic markers and the possible genetic/epigenetic mechanisms underlying their dysregulation in different subtypes of glioblastoma (GBM)." (PMID 30848102, 2019). "Galectin-3 is an important target molecule of SFN in glioblastoma cells invasion progress." (PMID 27026929, 2016). "We had shown a focal accumulation of galectin-3 in glioblastomas." (PMID 24764473, 2013).
glioblastoma (continued). "Additionally, previous studies have stated that CD276 (B7-H3), GATA3, and galectin-3 enable prognosis prediction in glioblastoma, and that correlation between lower balance of Th2 helper T-cells and lower expression of PD-L1/PD-1 axis genes also estimate prognosis in glioblastoma." (PMID 39707577, 2024). "In the current study, we tried to study the expression of LGALS3 and LGALS3BP, their potential as prognostic markers and the possible genetic/epigenetic mechanism underlying their dysregulation in different subtypes of glioblastoma (GBM), by using large online databases." (PMID 30848102, 2019). "Compared to normal brain tissues, LGALS1, LGALS3, and LGALS9 were significantly overexpressed in glioblastoma samples, with LGALS9 exhibiting the highest transcript abundance." (PMID 41516291, 2025). "Consistent with our UALCAN analysis, LGALS1, LGALS3, and LGALS9 were also overexpressed in glioblastoma." (PMID 41516291, 2025). "Our study highlights the role of LGALS1, LGALS3, and LGALS9 in glioblastoma invasion and migration via the induction of T cell apoptosis, protein homeostasis, and the maintenance of the ECM." (PMID 41516291, 2025). "We identified LGALS1, LGALS3, and LGALS9 as significantly upregulated in glioblastoma, with their overexpression correlating with adverse patient survival." (PMID 41516291, 2025). "This study provides a comprehensive, family-wide analysis of galectins in glioblastoma, revealing that LGALS1, LGALS3, and LGALS9 are consistently overexpressed and strongly associated with adverse survival, immune dysregulation, and tumour-promoting pathways." (PMID 41516291, 2025). "In glioblastoma multiforme (GBM), expression of galectin-3 on CSCs mediates immunosuppression by inducing T cell apoptosis." (PMID 36810098, 2023). "This, in combination with analysis of glioblastoma formalin-fixed paraffin-embedded tissue samples identified a nine-gene signature including IGFBP-2, chitinase-3-like protein 1 (CHI3L1)/YKL-40, galectin 3 (LGALS3) and OLIG2 that was predictive of worse clinical outcomes." (PMID 40429889, 2025). "Notably, IL-6 and the IL-6 signaling cascade support glioblastoma tumorigenesis and stemness, and we identified that genes involved in the IL-6 signaling pathway, such as ANXA1, LGALS3, and EGFR, were enriched in ICI non-responders pre-ICI 28–30." (PMID 40161763, 2025).